H2AC20 (H2A clustered histone 20)
Description:
Core component of nucleosome. Nucleosomes wrap and compact DNA into chromatin, limiting DNA accessibility to the cellular machineries which require DNA as a template. Histones thereby play a central role in transcription regulation, DNA repair, DNA replication and chromosomal stability. DNA accessibility is regulated via a complex set of post-translational modifications of histones, also called histone code, and nucleosome remodeling.
Synonyms: H2AFQ; HIST2H2AC; H2A/q; H2A; H2A-GL101
Tractability: Small molecule: a structure with a bound ligand is known. PROTAC: UniProt records ubiquitination sites on it; ubiquitination databases record sites on it.
Gene: Protein-coding gene on chromosome 1 (149,886,918 to 149,887,411, forward strand). Ensembl gene ENSG00000184260.
Subcellular location: Nucleus; Chromosome
Subcellular location (Human Protein Atlas): Nucleoplasm
Pathways (Reactome):
Gene expression (Transcription): B-WICH complex positively regulates rRNA expression; DNA methylation; ERCC6 (CSB) and EHMT2 (G9a) positively regulate rRNA expression; MLL4 and MLL3 complexes regulate expression of PPARG target genes in adipogenesis and hepatic steatosis; NoRC negatively regulates rRNA expression; PRC2 methylates histones and DNA; RNA Polymerase I Promoter Escape; RNA Polymerase I Promoter Opening; RUNX1 regulates genes involved in megakaryocyte differentiation and platelet function; RUNX1 regulates transcription of genes involved in differentiation of HSCs; Regulation of endogenous retroelements by KRAB-ZFP proteins; Regulation of endogenous retroelements by Piwi-interacting RNAs (piRNAs); Regulation of endogenous retroelements by the Human Silencing Hub (HUSH) complex; SIRT1 negatively regulates rRNA expression; Transcriptional regulation by small RNAs
Chromatin organization: CHD1 and CHD2 subfamily; CHD6, CHD7, CHD8, CHD9 subfamily; ChAHP complex assembly; HATs acetylate histones; HDACs deacetylate histones; Interaction of NuRD complexes with transcription factors; NuRD complex assembly; RMTs methylate histone arginines
Cell Cycle: Condensation of Prophase Chromosomes; Deposition of new CENPA-containing nucleosomes at the centromere; Inhibition of DNA recombination at telomere; Packaging Of Telomere Ends
DNA Repair: Cleavage of the damaged purine; Cleavage of the damaged pyrimidine; Recognition and association of DNA glycosylase with site containing an affected purine; Recognition and association of DNA glycosylase with site containing an affected pyrimidine
Disease: Defective pyroptosis; Dengue Virus-Host Interactions; HCMV Early Events; HCMV Late Events
Metabolism of proteins: Amyloid fiber formation; Metalloprotease DUBs; UCH proteinases; Ub-specific processing proteases
Signal Transduction: Activated PKN1 stimulates transcription of AR (androgen receptor) regulated genes KLK2 and KLK3
and 15 more pathways
Gene Ontology:
Molecular function: structural constituent of chromatin; DNA binding; protein heterodimerization activity
Biological process: heterochromatin formation
Cellular component: extracellular exosome; nucleoplasm; nucleus; nucleosome; chromosome
Genetic constraint (gnomAD): Loss-of-function variants: 7 observed, 7.64 expected, observed/expected ratio (o/e) 0.92, 90% interval 0.52 to 1.66. That is too few expected variants to judge how well the gene tolerates losing a copy. Missense variants: 127 observed, 190.26 expected, observed/expected ratio (o/e) 0.67, 90% interval 0.58 to 0.77. Synonymous variants: 97 observed, 80.77 expected, observed/expected ratio (o/e) 1.2, 90% interval 1.02 to 1.42.
Homologues: Orthologues: chimpanzee H2AC20 (100% identical), macaque H2AC20 (100% identical), mouse H2ac20 (100% identical), pig H2AC20 (100% identical), zebrafish h2af1al (72% identical), Caenorhabditis elegans htas-1 (53% identical). Paralogues in human: H2AC18 (98% identical), H2AC19 (98% identical), H2AC11 (97% identical), H2AC13 (97% identical), H2AC15 (97% identical), H2AC16 (97% identical), H2AC17 (97% identical), H2AC6 (97% identical), H2AJ (97% identical), H2AC12 (96% identical), H2AC25 (96% identical), H2AC7 (96% identical), and 15 more.
Diseases named in the same sentence as H2AC20 in open-access papers:
H2AC20 is named in the same sentence as 11 diseases in open-access papers, as found by Europe PMC text mining. Sharing a sentence is not in itself a finding about the gene and the disease. The quoted sentences say what the papers report.
breast carcinoma (3 papers, 2024 to 2025). "Histone H2A (H2AC20) mRNA levels are increased in breast cancer cells and increased H2AC20 expression correlates with higher proliferation." (PMID 38926604, 2024).
gastric cancer (1 paper, 2025). A primary or metastatic malignant neoplasm involving the stomach. "ASF1B was first found to promote gastric cancer progression by downregulating H2AC20 to affect the activation of PI3K/AKT and ERK1/2 signaling pathways." (PMID 40041497, 2025). "We overexpressed H2AC20 in ASF1B-OE gastric cancer cells and discovered that H2AC20 can reverse the promoting effects of ASF1B on gastric cancer cell proliferation and invasion, as well as the influence of ASF1B on the cell cycle and apoptosis." (PMID 40041497, 2025). "H2AC20 was overexpressed in ASF1B-overexpressing gastric cancer cells." (PMID 40041497, 2025).
RIDDLE syndrome (1 paper, 2021). A syndrome of increased radiosensitivity, immunodeficiency, mild motor control and learning difficulties, facial dysmorphism, and short stature. "H2AC20 gene encodes a replication-dependent histone that is a member of the histone H2A family and is associated with Riddle Syndrome and Xeroderma Pigmentosum Group E disease." (PMID 34992636, 2021).
cancer (3 papers, 2020 to 2025). A tumor composed of atypical neoplastic, often pleomorphic cells that invade other tissues. "Whether this is related to the different roles of H2AC20 in different cancer backgrounds and at different stages of cancer development, existing studies have not given a clear explanation and further investigation is needed." (PMID 40041497, 2025).
H2AC20 also shares sentences with these, for which no sentence is quoted: COVID-19 (1 paper); endometriosis (1); liver fibrosis (1); malaria (1); prostate carcinoma (1); systemic lupus erythematosus (1); tumor (1).